ALKBH5 (alkB homolog 5, RNA demethylase)
Diseases named in the same sentence as ALKBH5 in open-access papers (continued):
Sharing a sentence is not in itself a finding about the gene and the disease.
glioblastoma (continued). "ALKBH5 enhances self-renewal and oncogenesis of glioblastoma by sustaining FOXM1 expression, and it also mediates the hypoxia-induced stem cell phenotypes of breast cancer." (PMID 32772918, 2020). "In glioblastoma stem-like cells (GSCs), the m6A eraser ALKBH5 is highly expressed and predicts poor survival of patients with glioblastoma (GBM)." (PMID 32443966, 2020). "Recently, the other demethylase, ALKBH5, was shown to potentiate tumourigenicity of glioblastoma by enhancing FOXM1 expression." (PMID 31632489, 2019). "Previous studies indicated that ALKBH5 maintains tumorigenicity and proliferation of BC stem cells and glioblastoma stem-like cells." (PMID 30953473, 2019). "Functionally, METTL14 was reported as a tumor suppressor for glioblastoma and hepatocellular carcinoma and ALKBH5 as oncogene for glioblastoma and BC." (PMID 30953473, 2019). "ALKBH5 is highly expressed in glioblastoma stem-like cells (GSCs), and the downregulation of expression inhibited the proliferation of patient-derived GSCs." (PMID 30987661, 2019). "ALKBH5 is highly expressed in glioblastoma, and ALKBH5 silencing inhibits the proliferation of glioblastoma." (PMID 31808521, 2019). "Recent studies found m6A-modifying enzymes Mettl3, Alkbh5, and Fto to be involved in regulating progression of glioblastoma, indicating that m6A epitranscriptomic regulation plays roles in the nervous system." (PMID 29855337, 2018). "ALKBH5 is N6-methyladenosine demethylase and recently reported to be involved in the tumorigenicity of glioblastoma stem-like cells." (PMID 30286143, 2018). "ALKBH5, another demethylase identified earlier, regulates spermatogenesis and maintains tumorigenicity of glioblastoma stem-like cells." (PMID 29855379, 2018). "According to these findings, it was concluded that ALKBH5 is required for glioma stem cell proliferation and suggest an important role for m6A in the generation of glioblastomas." (PMID 30279357, 2018). "ALKBH5 is highly expressed in cell lines or patient-derived primary glioblastoma cultures enriched for GSCs, and knockdown of ALKBH5 impairs GSC self-renewal in vitro and decreases proliferation and tumorigenesis of GSCs in vivo." (PMID 28533023, 2017). "Additionally, in glioblastoma stem-like cells (GSCs), ALKBH5-demethylated FOXM1 nascent transcripts promote the proliferation of GSCs." (PMID 40001461, 2025). "Pharmacologic targeting of ALKBH5 enhanced the anti-tumor efficacy of EGFR inhibitor erlotinib, suggesting that ALKBH5 may function as a potential therapeutic target in combination with EGFR for glioblastoma patients." (PMID 40097417, 2025). "However, the roles of ALKBH5 in glioblastoma stemness are independent from GCLM, because modulating GCLM expression using shRNAs or an inhibitor did not significantly impact the levels of GSC stemness markers or self-renewal." (PMID 38398118, 2024). "ALKBH5 is highly expressed in glioblastoma stem cell‐like cells." (PMID 39006762, 2024). "ALKBH5, a m6A demethylase, modulates target gene expression, generates an immunosuppressive tumor microenvironment and contributes to the efficacy of immunotherapy in melanoma, colorectal cancer and glioblastoma." (PMID 38589927, 2024). "Moreover, ALKBH5, another m6A demethylase, exhibits high expression in Glioblastoma stem-like cells (GSCs), and decreased expression of ALKBH5 in combination with FOXM1-AS impairs GSC tumorigenesis via the FOXM1 axis." (PMID 39372951, 2024). "ALKBH5 promotes the expression of the chemokine CXCL8/IL8 in human glioblastoma." (PMID 39726589, 2024). "Meanwhile, another recent study showing the forced expression of malate dehydrogenase 2(MDH2) raised m6A levels and suppressed ALKBH5 activity in glioblastoma stem cells, which could be restored by alpha-ketoglutarate supplementation." (PMID 39759516, 2024). "However, the trial of an ALKBH5 inhibitor in the glioblastoma cell line A-172 demonstrated negligible effects." (PMID 37444417, 2023).
glioblastoma (continued). "ALKBH5 can promote the proliferation, migration, and invasion of glioblastoma multiforme." (PMID 37511932, 2023). "In addition, the TCGA database showed that co‐high expression of ALKBH5 and TIRAP is associated with poor prognosis in patients with glioblastoma and thyroid cancer receiving radiotherapy." (PMID 36792369, 2023). "However, ALKBH5 has been demonstrated to be an oncogene in glioblastoma through the modification of FOXM1, in breast cancer through m6A demethylation of NANOG, and in acute myeloid leukemia via AXL m6A modification." (PMID 35395767, 2022). "Recent research showed that ALKBH5 mRNA and protein expression were upregulated in glioblastoma stem-like cells (GSCs) and ALKBH5 could maintain the tumorigenicity of GSCs by maintaining FOXM1 expression." (PMID 35444654, 2022). "Interestingly, ALKBH5 co-expressed with the typical stemness marker for glioblastoma, SOX2 and Nestin in tumor tissue." (PMID 35625706, 2022). "It was recently reported that in glioblastoma stem-like cells (GSCs), ALKBH5 as a m6A eraser could demethlyse FOXM1 nascent transcripts and enhanced FOXM1 expression." (PMID 35331183, 2022). "In addition, another team validated that tumor-intrinsic ALKBH5 was responsible for the recruitment of tumor-associated macrophage (TAM) and immunosuppressive phenotypes under hypoxic conditions in glioblastoma multiforme." (PMID 35628623, 2022). "Interestingly, our findings are different from some other reports showing that ALKBH5 promoted the proliferation of some cell types, including human glioblastoma stem-like cells, human renal cell carcinoma cells, and human lung adenocarcinoma cells." (PMID 35130626, 2022). "A study reported that ALKBH5 could maintains tumorigenicity of glioblastoma stem-like cells by sustaining FOXM1 expression." (PMID 36008805, 2022). "The m6A-demethylase ALKBH5 has been shown to be overexpressed in patient-derived glioblastoma stem cells and may influence radio-resistance via regulation of DNA damage response genes including Chk1." (PMID 34093133, 2021). "Moreover, ALKBH5 is involved in glioblastoma to repress tumorigenesis, in spermatogenesis and in male fertility." (PMID 34093133, 2021). "Furthermore, two research groups have demonstrated that ALKBH1 and ALKBH5 are related to glioblastoma." (PMID 33744868, 2021). "The survival fractions after IR were significantly decreased in all GBMSCs transfected with the specific ALKBH5 siRNA compared to the control siRNA, indicating that downregulation of ALKBH5 mRNA expression radiosensitizes GBMSCs derived from human glioblastoma biopsy specimens." (PMID 33375621, 2020). "Their work showed that the demethylase ALKBH5 is highly expressed in GSCs, and, notably, overexpressed in those cells not only in comparison with healthy control tissues or cells, but also compared to established glioblastoma cell lines." (PMID 32316617, 2020). "Increased ALKBH5 indicates poor prognosis of patients with glioblastoma while ALKBH5 depletion interferes with self‐renewal ability and inhibits the proliferation and tumorigenesis of GSCs by sustaining FOXM1 expression via ALKBH5‐mediated m6A demethylation of FOXM1 nascent transcripts." (PMID 33029866, 2020). "However, Zhang et al48 reported that ALKBH5 maintains tumorigenicity of glioblastoma stem-like cells." (PMID 32742465, 2020). "However, “erasers” FTO and ALKBH5 have been shown to be more important in glioblastoma, AML, and BRC." (PMID 32547941, 2020). "ALKBH5 stabilizes FOXM1 mRNA to promote tumorigenesis in glioblastoma." (PMID 32021563, 2020). "In glioblastoma, increase in ALKBH5 expression is considered a poor prognostic factor." (PMID 32709063, 2020). "Besides, the up-regulated ALKBH5 predicted poor survival in glioblastoma patients and NSLCL patients." (PMID 32742194, 2020). "The oncogenic role of ALKBH5 was also reported in glioblastoma." (PMID 33584787, 2020).
glioblastoma (continued). "The impact of m6A modification on tumorigenesis in various types of cancer is exposed through deregulation of different components of m6A machinery, such as upregulation of ALKBH5 in glioblastoma stem cells as an indication of poor prognosis, or oncogenic role of FTO in leukemic cell transformation." (PMID 31947544, 2020). "In addition, the high expression of ALKBH5 in glioblastoma can lead to stem-like cell proliferation and tumorigenesis." (PMID 32682400, 2020). "Interestingly, it has also been shown that, in glioblastoma stem-like cells (GSCs), the m6A demethylase ALKBH5 is highly expressed, and the depletion of ALKBH5 and FOXM1-AS disrupts GSC tumorigenesis through the reduction FOXM1 expression." (PMID 31316981, 2019). "Another role of ALKBH5 is in glioblastoma stem-like cells (GCSs)." (PMID 30654440, 2019). "Similarly, silencing ALKBH5 in glioblastoma stem cells suppressed cell proliferation via enhancing FOXM1 expression." (PMID 31333841, 2019). "ALKBH5 regulated the malignant behavior of breast cancer and glioblastoma." (PMID 30987661, 2019). "Furthermore, ALKBH5 also plays an important role in maintaining glioblastoma proliferation and tumorigenesis by enhancing mRNA expression of FOXM1, a pivotal transcription factor for glioblastoma stem cell self-renewal." (PMID 30212448, 2018). "High expression of ALKBH5 in glioblastoma patients predicts poor prognosis." (PMID 28533023, 2017). "Equally, the m6A “eraser” ALKBH5 controls the demethylation of PD-L1 mRNA; loss of ALKBH5 destabilizes PD-L1 transcripts via enhanced YTHDF2 binding, increasing tumor vulnerability to T-cell–mediated lysis and potentiating responses to PD-1 blockade in preclinical glioblastoma models." (PMID 41280938, 2025). "Aberrant activation of ALKBH5 in glioblastoma (GBM) plays a critical role in tumor growth and progression, and studies have identified a mechanism of regulation of ALKBH5 by USP36." (PMID 39192357, 2024). "However, METTL3 and ALKBH5 were both found to maintain the growth of glioblastoma cells." (PMID 38398118, 2024). "In addition, ALKBH5 has high expression in the embryonic stage and glioblastoma stem-like cells (GSCs), revealing that ALKBH5 may play an indispensable role in brain development and GSC proliferation." (PMID 36187229, 2022). "In addition, through screening on a 3D proteome-wide scale and activity evaluation, MV1035 could reduce U87 glioblastoma cell line migration as a new ALKBH5 inhibitor." (PMID 36120320, 2022). "However, whether m6A demethylases ALKBH5 participate in regulating the tumor immune microenvironment and the efficacy of immunotherapy in glioblastoma remain unknown." (PMID 36566230, 2022). "However, another leukemia cell line, Jurkat, and glioblastoma A-172 cells had low to no susceptibility, suggesting ALKBH5 suppression by small-molecule inhibitors as a feasible cancer-cell-type-selective anti-proliferative approach." (PMID 35063010, 2022). "In addition, recent research showed that m6A RNA methylation can regulate the self-renewal and tumorigenesis of glioblastoma stem cells, and m6A demethylase ALKBH5 can maintain tumorigenicity of glioblastoma stem-like cells by sustaining FOXM1 expression and cell proliferation program." (PMID 34054873, 2021). "Besides, the inhibition of ALKBH5 could reduce the proliferation of glioblastoma stem-like cells via FOXM1 axis." (PMID 33240891, 2020). "Knockdown of ALKBH5 reduced the growth of glioblastoma, which could be recovered by catalytically wild-type ALKBH5 but not H204A-mutated ALKBH589." (PMID 32346127, 2020). "In addition, the “writers” METTL3 and METTL14 were more predisposed to mutation or CNV than the other genes in ccRCC, while alterations of the “erasers” FTO and ALKBH5 were proved to be more important in breast cancer, glioblastoma and hematological malignancies." (PMID 30877265, 2019). "Additionally, ALKBH5 maintains tumorigenicity of glioblastoma stem-like cells (GSCs)." (PMID 30149601, 2018).
glioblastoma (continued). "Conversely, ALKBH5 repression decreased tumorsphere formation and downregulated the TFs SOX2, Nanog, and Oct4, contributing to the self-renewal capacity of glioblastoma stem cells and breast CSCs." (PMID 38704599, 2024). "In glioblastoma (GBM), aberrant activation of ALKBH5 plays a critical role in tumor growth and progression." (PMID 39192357, 2024). "ALKBH5 enhances the expression of FOXM1 via demethylation, promoting stem‐like cell proliferation and tumourigenesis in glioblastoma." (PMID 38545841, 2024). "The ALKBH5–GCLM axis suppressed ferroptosis and promoted tumor cell viability, thereby increasing survival of the mice bearing glioblastoma." (PMID 38398118, 2024). "In glioblastoma multiforme (GBM), ALKBH5 regulated the m6A modification of lncRNA NEAT1, leading to increased expression of interleukin-8 (IL-8), which promoted macrophage recruitment." (PMID 39220683, 2024). "In the field of cancer research, ALKBH5 was reported to enhance self‐renewal and proliferative ability of cancer stem cells (CSC) in glioblastoma." (PMID 37203239, 2023). "According to the WHO classification, ALKBH5 and PYCR2 were more highly expressed in grade IV glioblastoma." (PMID 37325047, 2023). "ALKBH5 can stabilize the expression of the target gene FOXM1 mRNA by reducing the levels of m6A, thereby inducing the occurrence of glioblastoma." (PMID 37805597, 2023). "There is evidence that ALKBH5 can enhance SOX2 expression by demethylating the mRNA of SOX2, thereby promoting resistance to Temozolomide in glioblastoma." (PMID 37007161, 2023). "The target of ALKBH5, OGDH, has been shown to inhibit the proliferation of glioblastoma and gastric cancer cells." (PMID 37742191, 2023). "ALKBH5 has been verified to demethylate FOXM1 nascent transcripts by the FOXM1 3′-UTR region, resulting in enhanced FOXM1 expression in glioblastoma stem-like cells." (PMID 35279083, 2022). "In glioblastoma stem cells, the lncRNA FOXM1-AS has been illustrated to influence interactions among FOXM1 and ALKBH5 to shape cell maintenance." (PMID 36277972, 2022). "ALKBH5 modulates some transcripts of 3’UTR m6A, mediates hypoxia-inducible factor (HIF)-dependent breast CSC phenotype, and regulates glioblastoma growth and carcinogenesis via the ALKBH5-FOXM1 pathway, thereby indicating its essential role in tumorigenesis." (PMID 36466802, 2022). "Recent advances have highlighted that FTO and ALKBH5 play an oncogenic role in various cancers, such as acute myeloid leukemias (AML), glioblastoma, and breast cancer." (PMID 35628623, 2022). "In this scenario, tumor-intrinsic ALKBH5 drives TAM infiltration and induces M2 polarization, leading to immunosuppression and tumor progression in glioblastoma multiforme." (PMID 35063010, 2022). "The correlation between ALKBH5 mRNA expression levels and the prognosis of patients with primary glioma, recurrent glioma, low grade glioma (LGG) or glioblastoma (GBM) was investigated using the CGGA and TCGA datasets." (PMID 35444654, 2022). "ALKBH5 has been reported to demethylate FOXM1 nascent transcripts and promote FOXM1 expression in glioblastoma." (PMID 33428593, 2021). "FOXM1-AS, a lncRNA antisense to FOXM1, promotes the interaction between the m6A demethylase ALKBH5 and the FOXM1 nascent transcripts, leading to the removal of m6A from FOXM1 transcripts to enhance FOXM1 expression in glioblastoma." (PMID 34803608, 2021). "ALKBH5 is necessary for GSC self-renewal, and increased ALKBH5 expression typically indicates a poor prognosis in patients with glioblastoma (GBM), whereas ALKBH5 deletion can inhibit GSC proliferation and tumorigenesis." (PMID 34745269, 2021). "Intriguingly, reasons of m6A dysregulation in CSCs are different among various types of cancer, considering the roles of FTO, ALKBH5, and METTL3 in glioblastoma stem cells and of METTL14 and FTO in leukemia stem cells." (PMID 32676121, 2020).
glioblastoma (continued). "We first analyzed the correlation between ALKBH5 and YAP1 expression using the glioblastoma database of the Cancer Genome Atlas, (TCGA)." (PMID 33375621, 2020). "In detail, FOXM1-AS was localized in the same cellular fraction as ALKBH5 and FOXM1 nascent transcripts, and further studies indicated that FOXM1-AS up-regulated FOXM1 expression and played an important role in glioblastoma cells tumorigenesis." (PMID 32742194, 2020). "Regarding glioblastoma, ALKBH5 provided a deep insight into critical roles of m6A methylation though enhancing the expression of FOXM1, and promoted tumorigenesis in glioblastoma." (PMID 32742194, 2020). "lncRNA FOXM1-AS promotes the interaction of m6A demethylase ALKBH5 with FOXM1 nascent transcripts, which enhances tumorigenicity of glioblastoma stem-like cells." (PMID 32021563, 2020). "While our manuscript was in preparation, a paper was published reporting the possibility of impairing the in vitro migration and invasiveness of the U87MG glioblastoma cell line, by the supplementation of MV1035, an inhibitor of ALKBH5." (PMID 32316617, 2020). "In glioblastoma, elevated ALKBH5 reduces m6A methylation and facilitates expression of oncogene FOXM1, leading to enhancement of glioblastoma stem-like cells (GSCs) self-renewal and tumorigenicity." (PMID 31801551, 2019). "The exogenous expression of ALKBH5 effectively rescued the impacts of USP14 KD on RNA m6A methylation, GSC proliferation, sphere-forming frequency in vitro, and the tumorigenicity of orthotopic glioblastoma xenografts." (PMID 39990235, 2025). "Similarly, ALKBH5 inhibitors—such as MV1035 analogs—have been shown to reduce PD-L1 expression and rescue anti-tumor immunity in glioblastoma allografts, highlighting the potential of “eraser” blockade to overcome immune escape." (PMID 41280938, 2025). "Our study suggesting a role of ALKBH5- and FTO-ATF4 axes in cancer resistance is also consistent with the emerging role of either demethylase in the development of various types of tumors, including breast, gastric, and glioblastoma." (PMID 39199320, 2024). "Individual m6A RNA methylation regulators, including METTL3, ALKBH5, YTHDF2, and IGF2BP3, have been assessed in patient datasets to examine their expression levels across normal tissues, lower-grade gliomas, and glioblastomas, as well as their prognostic significance." (PMID 38398118, 2024). "In glioblastoma, FOXM1 expression is up‐regulated by m6A demethylase ALKBH5." (PMID 38967523, 2024). "Both ALKBH5 and ALKBH2 are highly expressed in glioblastoma and this is the reason why we started our experimental validation from these two proteins, while an in-depth analysis and validations for the other top-ranked potential targets will be the matter of future studies." (PMID 35053068, 2022). "MV1035, an ALKBH5 inhibitor, can reduce U87-MG migration and invasiveness via down-regulation of CD73, which is an extrinsic protein involved in the generation of adenosine and overexpressed in glioblastoma." (PMID 35625706, 2022). "ALKBH5 could target transcription factor FOXM1 and promote the tumour proliferation of glioblastoma stem‐like cells, which could be enhanced by a nuclear lncRNA FOXM1‐AS." (PMID 35340126, 2022). "For example, ALKBH5 functions as a tumor suppressor in ESCC (this study), hepatocellular carcinoma, pancreatic cancer, and lung cancer, whereas it exerts pro-tumorigenic effects on leukemia, glioblastoma, and breast cancer." (PMID 34491904, 2021). "The comparison between glioblastoma stem cells and tumour tissues derived from the same patient evidenced ALKBH5 mRNA strong enrichment in the stem cells, again pointing at a role for ALKBH5 not merely in glioblastoma, but rather in its cells of origin." (PMID 32316617, 2020). "FOXM1-AS promoted the interaction of ALKBH5 with FOXM1 nascent RNA, leading to demethylation and elevated expression of FOXM1 in glioblastoma stem-like cells, therefore enhancing self-renewal and tumorigenesis of glioblastoma." (PMID 32209098, 2020).